NT5E (5'-nucleotidase ecto)
Diseases named in the same sentence as NT5E in open-access papers (continued):
Sharing a sentence is not in itself a finding about the gene and the disease.
colon carcinoma (23 papers, 2013 to 2025). "In the present study, we investigated the role of ABCC6 in colon cancer evaluating the effect of Quercetin and Probenecid, inhibitors of the ectonucleotidase NT5E and ABCC6, respectively, on migration rate of Caco2 and HT29 cell lines." (PMID 35645325, 2022). "Rutin targets two proteins, namely NT5E and EGFR, which both interact with established colon cancer drug targets and two proteins that are part of the colon cancer prognostic signature gene set (CYP1B1 and ALOX5)." (PMID 24886433, 2014).
COVID-19 (23 papers, 2020 to 2026). A disease caused by infection with severe acute respiratory syndrome coronavirus 2. "We observed significant upregulation of CD39 (ENTPD1) and CD73 (NT5E), which was confirmed by immunohistochemical experiments, both of which are able to hydrolyze ATP, in SCTs of the COVID-19 group." (PMID 38441496, 2024). "Herein, we detected the gene expression of ENPP1, ENPP2, ENPP3, ENTPD1 (CD39), ENTPD5, and NT5E (CD73) in the whole blood of COVID-19 patients." (PMID 36248842, 2022). "Simultaneously, inhibitory markers were upregulated in patients with COVID-19 that potentially counterbalance the hyperactivation of the immune response, such as NT5E/CD73, PD1 and TNFRSF8/CD30." (PMID 37047248, 2023).
cervical carcinoma (18 papers, 2017 to 2025). A carcinoma arising from either the exocervical squamous epithelium or the endocervical glandular epithelium. "Our data showed that the NT5E gene, that encoded CD73, is hypermethylated, leading to a decreased CD73 expression in cervical cancer cells compared to normal cells." (PMID 39762204, 2025). "We also showed that the reduced CD73 expression in cervical cancer might be due to hypermethylation in the NT5E gene." (PMID 39762204, 2025). "Furthermore, TNFRSF12A (TWEAK-R), NT5E (CD73), and TGFB1/TGFBR1 were genes where low expression was significantly associated with increased survival in both cervical cancer and HNSCC, demonstrating that high expression of these immune genes is detrimental to outcome." (PMID 36575316, 2023).
lung adenocarcinoma (18 papers, 2017 to 2025). A carcinoma that arises from the lung and is characterized by the presence of malignant glandular epithelial cells. "(A) Expression of NT5E (CD73) in lung adenocarcinoma (N=483) and normal lung (N=387) based on analysis of TCGA patient data." (PMID 35815945, 2022).
autoimmune disease (16 papers, 2014 to 2025). A disorder resulting from loss of function or tissue destruction of an organ or multiple organs, arising from humoral or cellular immune responses of the individual to their own tissue constituents. "Low expression of NT5E/CD73 on FoxP3+ Tregs might contribute to a dysregulated immune response in autoimmune diseases." (PMID 33613285, 2020).
Autoimmunity (15 papers, 2017 to 2025). The occurrence of an immune reaction against the organism's own cells or tissues. "In fact, rare human individuals have now been identified with loss of function mutations in the NT5E gene, leading to a lack of CD73 protein and enzymatic activity, who are characterized by arterial calcification due to vascular dysplasia, but with no reported manifestations of autoimmunity." (PMID 33477692, 2021).
endometrial carcinoma (15 papers, 2014 to 2026). A malignant tumor arising from the epithelium that lines the cavity of the uterine body. "In early-stage endometrial cancer, TGF-β1 has been shown to upregulate NT5E expression, which contributes to the maintenance of epithelial cell integrity and thus inhibits tumor progression." (PMID 40463372, 2025).
liver fibrosis (11 papers, 2018 to 2024). "Among these, the mRNA levels of nine genes, including USB1, NT5E, RORA, SDK1, and IL10, were significantly up-regulated, suggesting their involvement in the miRNA-30-mediated regulation of host hepatic fibrosis." (PMID 39139565, 2024).
head and neck cancer (9 papers, 2019 to 2025). A primary or metastatic malignant neoplasm affecting the head and neck. "The overexpression of NT5E was also associated with poor prognosis, and was related to tumor development and invasion in pancreas, prostate, bladder and head and neck cancer." (PMID 36569293, 2022).
periodontitis (7 papers, 2023 to 2025). An acute or chronic inflammatory process that affects the tissues that surround and support the teeth. "In the present study, we demonstrated for the first time that the ectonucleotidase CD73 [also known as 5′-nucleotidase ecto (NT5E)] has a protective role in periodontitis." (PMID 38152410, 2023).
epilepsy (6 papers, 2020 to 2025). A brain disorder characterized by episodes of abnormally increased neuronal discharge resulting in transient episodes of sensory or motor neurological dysfunction, or psychic dysfunction. "Fourteen epilepsy-associated genes were identified as potential targets of ADORA2A in epilepsy, and four key genes including NT5E, ENTPD1, ADA, and ADK were mainly involved in the “negative regulation of neuron death” and “purine nucleoside biosynthetic process” biological processes." (PMID 33262686, 2020).
heart failure (6 papers, 2017 to 2024). Inability of the heart to pump blood at an adequate rate to meet tissue metabolic requirements. "NT5E, also known as CD73, is an enzyme involved in the purinergic signaling pathway and has been linked to heart failure." (PMID 38612670, 2024).
injury (6 papers, 2011 to 2023). Damage inflicted on the body as the direct or indirect result of an external force, with or without disruption of structural continuity. "PAP deficient (Pap-/-) and NT5E deficient (Nt5e-/-) mice have similar behavioral phenotypes, including enhanced nociceptive sensitization following nerve injury and following peripheral inflammation." (PMID 22011440, 2011).
osteoporosis (6 papers, 2016 to 2025). A condition of reduced bone mass, with decreased cortical thickness and a decrease in the number and size of the trabeculae of cancellous bone (but normal chemical composition), resulting in increased fracture incidence. "SPP1 signalling and COL1A1 signalling in osteoporosis were previously reported; and NT5E, HTRA1 and ANGPT1 signalling pathways reported here require further confirmation." (PMID 27690016, 2016). "Elevated SPP1, COL1A1 and NT5E proteins may be secreted from the pituitary tumor to directly target the skeletal system, with resultant osteoporosis, while downregulated HTRA1 and ANGPT1 may deregulate in bone formation and development." (PMID 27690016, 2016). "SPP1 (secreted phosphoprotein 1), COL1A1 (collagen type I α 1 chain), NT5E (5′-nucleotidase ecto), HTRA1 (HtrA serine peptidase 1) and ANGPT1 (angiopoietin 1) and their signalling pathways involving osteoporosis in CD patients are identified." (PMID 27690016, 2016). "Secreted phosphoprotein 1 (SPP1), collagen type I α 1 chain (COL1A1), 5′-nucleotidase ecto (NT5E), HtrA serine peptidase 1 (HTRA1) and angiopoietin 1 (ANGPT1) and their signalling pathways are shown to be involved in osteoporosis in CD patients." (PMID 27690016, 2016). "Although the molecluar mechanism of NT5E, HTRA1 and ANGPT1 in osteoporosis has not been studied yet, the signaling pathways regulated by them are closely related to the signal pathways of bone development and formation." (PMID 27690016, 2016).
Stroke (6 papers, 2017 to 2025). Sudden impairment of blood flow to a part of the brain due to occlusion or rupture of an artery to the brain. "Choroid plexus tissues were collected and analyzed for Vcam1, Madcam1, Cx3cl1, Ccl2, Nt5e, and Ifnγ expression at different timepoints after stroke using qPCR." (PMID 28754163, 2017). "However, there is a significantly higher expression of two ectonucleotidases (ENTPD-1, CD39 and NT5E, CD73) in the ipsilateral hemisphere 7 days after stroke." (PMID 40332314, 2025).
lymphoma (5 papers, 2013 to 2025). A malignant (clonal) proliferation of B- lymphocytes or T- lymphocytes which involves the lymph nodes, bone marrow and/or extranodal sites. "NT5E, a gene encoding the CD73 enzyme, has been found to be upregulated at multiple levels to support tumor growth in several subtypes of solid tumors, as well as in myeloma, but in lymphoma its description is scant." (PMID 40461625, 2025).
oral squamous cell carcinoma (5 papers, 2018 to 2024). "The expression level of CD73/NT5E in oral cavity squamous cell carcinoma versus matched normal tissue." (PMID 29514610, 2018).
calcification (4 papers, 2017 to 2025). Process by which organic tissue becomes hardened by the physiologic deposit of calcium salts. "In contrast, calcifications resulting from Abcc6 inactivation were augmented by crossing Abcc6−/− mice with Nt5e−/− mice and Abcc6−/− mice have reduced Nt5e expression in their arteries." (PMID 28891970, 2017).
colorectal tumors (4 papers, 2015 to 2025). "However, three transcripts (SKAP1, ARHGAP24, and NT5E) were up-regulated in PMP but generally down-regulated in colorectal tumors." (PMID 25929336, 2015). "To validate this tumor-specific fibroblast infiltration, we analyzed the expression of stromal cell subtype markers CD24, CD26, NT5E, FAP, and FGFR2 in colorectal tumor and non-malignant large intestine samples by flow cytometry." (PMID 35365629, 2022).
metastatic colorectal cancer (4 papers, 2021 to 2025). "In agreement with our findings, another study identified the CD73 gene, NT5E, among a set of 110 candidate genes for which higher expression was associated with decreased likelihood of disease control in metastatic colorectal cancer patients treated with cetuximab monotherapy." (PMID 34165921, 2021).
myocarditis (4 papers, 2023 to 2025). Myocarditis is a condition that is characterized by inflammation of the heart muscle (myocardium). "In this study, based on large-scale proteomics data, we identified multiple pathogenic proteins involved in myocarditis, including NT5E, via MR." (PMID 40906170, 2025). "The aim of this study was to experimentally verify, through RNA sequencing (RNA-seq) and other analyses, that NT5E is an important factor in Reg3β-mediated macrophage polarization during myocarditis injury repair." (PMID 40906170, 2025). "Using Mendelian randomization (MR) analysis, we further identified that NT5E interacts with multiple plasma proteins influencing myocarditis progression through immune cells." (PMID 40906170, 2025).
pancreatic adenocarcinoma (4 papers, 2022 to 2025). "The increased expression of NT5E and its prognostic significance were confirmed through multiplex immunohistochemistry in pancreatic adenocarcinoma." (PMID 39911580, 2024).
Parkinson disease (4 papers, 2019 to 2023). A progressive degenerative disorder of the central nervous system characterized by loss of dopamine producing neurons in the substantia nigra and the presence of Lewy bodies in the substantia nigra and locus coeruleus. "In the brain, Nt5e can activate, rather than repress, microglia in a Parkinson’s disease model and contribute to neuronal toxicity." (PMID 31784610, 2019).
gallbladder adenocarcinoma (3 papers, 2014 to 2022). A carcinoma that arises from glandular epithelial cells of the gall bladder. "Then, an in-vivo study of gallbladder adenocarcinoma and chronic cholecystitis was performed to verify the results obtained in the microarray study and further investigate the role of NT5E and FcGBP in invasion and metastasis of gallbladder adenocarcinoma." (PMID 24310606, 2014). "The elevated expression of NT5E and decreased expression of FcGBP in gallbladder adenocarcinoma suggested that they are important markers for progression, clinical biological behavior and prognosis." (PMID 24310606, 2014). "Immunochemistry and clinicopathological results showed that the expression of NT5E and FcGBP in gallbladder adenocarcinoma is an independent marker for evaluation of the disease progression, clinical biological behaviors and prognosis." (PMID 24310606, 2014).
Obesity (3 papers, 2015 to 2022). Accumulation of substantial excess body fat. "Afterward, based on TFEA and qRT-PCR verification, we confirmed that SOCS3, ICAM-1, NT5E, MYC, CCL2, and PPARG were potential ORDEGs that linked obesity and OLF pathogenesis." (PMID 35712246, 2022). "Similar to Emr1, higher levels of Entpd1, Cd38, and Nt5e were found in BAT of ob/ob mice, while no obesity-associated changes in Ucp1 expression were detected." (PMID 33025427, 2020).
acute lung injury (2 papers, 2016 to 2024). A condition of lung damage that is characterized by bilateral pulmonary infiltrates (pulmonary edema) rich in neutrophils, and in the absence of clinical heart failure. "Similarly, in a model of acute lung injury (ALI), adoptive transfer of Nt5e-deficient (CD73-deficient) Treg cells failed to resolve ALI adequately, whereas transfer of wild-type Treg cells led to normal resolution." (PMID 27621729, 2016).
Generalized arterial calcification of infancy (2 papers, 2015 to 2020). "Deleterious mutations in human ABCC6, ENPP1, NT5E genes cause PXE, generalized arterial calcification of infancy (GACI), and arterial calcification respectively." (PMID 26375467, 2015).
schizophrenia (2 papers, 2024 to 2025). A major psychotic disorder characterized by abnormalities in the perception or expression of reality. "Further studies on the availability and activity of the hydrolyzing ENTPD and NT5E enzymes are warranted to fully understand their function in the pathology of schizophrenia." (PMID 39404420, 2024). "In the comparison including all schizophrenia and control subjects, the mRNA expression levels of ENT1, ENT2, ENTPD1, ENTPD3, and NT5E were not significantly different between the two sexes." (PMID 39404420, 2024).
undifferentiated pleomorphic sarcoma (2 papers, 2022). An undifferentiated soft tissue sarcoma characterized by the presence of a pleomorphic malignant cellular infiltrate. "Differential gene expression between radioresponsive myxoid liposarcoma (MLPS) and more radioresistant undifferentiated pleomorphic sarcoma (UPS) indicated UPS contained higher transcript levels of a number of immunotherapy targets (CD73/NT5E, CD39/ENTPD1, CD25/IL2RA, and 4–1BB/TNFRSF9)." (PMID 35558159, 2022).
zinc deficiencies (2 papers, 2018 to 2022). "For example, both high expression of TNAP, ENPP1, ENPP3, and NT5E/CD73 and low expression of ENTPD1/CD39 increase the susceptibility of cells to the effects of zinc deficiency on extracellular adenine-nucleotide metabolism." (PMID 30271993, 2018). "ZnT zinc transporters ZnT5 and ZnT6 heterodimers and ZnT7 homodimers may also increase vulnerability to zinc deficiencies as they are both required for TNAP and NT5E/CD73 activity." (PMID 36555806, 2022). "Zinc deficiency severely impairs the activities of major ectoenzymes (ENPP1, ENPP3, NT5E/CD73, and TNAP), and also strongly suppresses adenine-nucleotide hydrolysis in cell-membrane preparations or rat plasma, thereby increasing ATP and ADP levels and decreasing adenosine levels." (PMID 30271993, 2018). "The quantification of each adenine nucleotide and adenosine hydrolyzed from ATP revealed that the effects of zinc deficiency varied depending on the cell type, which can be attributed to the distinct expression pattern and level of ENTPD1/CD39, ENPP1, ENPP3, NT5E/CD73, TNAP, PAP, and their isozymes." (PMID 30271993, 2018). "Moreover, the expression pattern of ZNT5–ZNT6 heterodimers and ZNT7 homodimers may also contribute to the susceptibility to zinc deficiency, because both zinc-transporter complexes are indispensable for the activity of TNAP and NT5E/CD73." (PMID 30271993, 2018).
alopecia (1 paper, 2022). Hair loss usually from the scalp. "In our study, NT5E (CD73) was one identified as of the major target proteins of the medicinal herbs for alopecia treatment." (PMID 35181715, 2022). "Therefore, 20 vital medicinal herbs for alopecia treatment may act by modulating NT5E (CD73) to promote dermal microcirculation through the regulation of purinergic signaling by desphosphorylating extracellular AMP to adenosine in hair follicles and dermal papilla cells." (PMID 35181715, 2022).
endocarditis (1 paper, 2012). Inflammation of the endocardium. "In our animal model of endocarditis, we did show that Nt5e deletion attenuates virulence." (PMID 22685551, 2012). "Finally, Nt5e was determined to be a plausible virulence factor in a rabbit endocarditis model." (PMID 22685551, 2012).
energy metabolism disorders (1 paper, 2024). "Benzoylaconine holds promise as a therapeutic drug for addressing energy metabolism disorders in DCM with HF by targeting NRK and NT5E." (PMID 38510644, 2024).
esophageal adenocarcinoma (1 paper, 2025). A malignant tumor with glandular differentiation arising predominantly from Barrett mucosa in the lower third of the esophagus. "Background/Objectives: Hypoxia promotes esophageal adenocarcinoma (EAC) aggressiveness through stabilization of hypoxia-inducible factor-1α (HIF-1α), which regulates pro-survival, pro-metastatic, and immunosuppressive pathways, including the ectoenzyme CD73 (NT5E)." (PMID 41463265, 2025).
pulmonary arterial hypertension (1 paper, 2024). Pulmonary arterial hypertension (PAH) is a group of diseases characterized by mean pulmonary artery pressure >20 mmHg and elevated pulmonary arterial resistance leading to right heart failure. "The glycolysis genes (ACSS2, ALAS2, ALDH3A1, ADOC3, NT5E, and TALDO1) identified in this study play important roles in the development of pulmonary arterial hypertension, providing new evidence for the involvement of glycolysis in PAH." (PMID 38837574, 2024).
tuberculosis (1 paper, 2025). A chronic, recurrent infection caused by the bacterium Mycobacterium tuberculosis. "Notably, this research represents the first comprehensive identification of significant differential expression patterns of FHIT, MAN1C1, SLC4A7, NT5E, and other genes in patients with tuberculosis (TB)." (PMID 40524207, 2025). "Transcriptomic profiling identified five metabolically significant differentially expressed genes (FHIT, MAN1C1, SLC4C7, NT5E, AKR1C3; p < 0.05) that effectively distinguish between latent tuberculosis infection (LTBI) and active tuberculosis (TB)." (PMID 40524207, 2025).